ABCA11P (ATP binding cassette subfamily A member 11, pseudogene)
Synonyms: ABCA10P; EST1133530; FLJ14297; formerly ABCA11
Gene: Transcribed processed pseudogene on chromosome 4 (425,773 to 427,882, reverse strand). Ensembl gene ENSG00000251595.
Diseases named in the same sentence as ABCA11P in open-access papers:
ABCA11P is named in the same sentence as 3 diseases in open-access papers, as found by Europe PMC text mining. Sharing a sentence is not in itself a finding about the gene and the disease. The quoted sentences say what the papers report.
glioblastoma multiforme (1 paper, 2023). "For instance, ABCA11P is associated with reduced OS in both oesophageal carcinoma and glioblastoma multiforme." (PMID 38117798, 2023).
meningioma (1 paper, 2020). A generally slow growing tumor attached to the dura mater. "Besides, potential roles of ABCA11P, ZNF732, and ZNF876P are novel in meningioma recurrence." (PMID 32923390, 2020).
ABCA11P also shares sentences with these, for which no sentence is quoted: cancer (1 paper).